RAB14 (RAB14, member RAS oncogene family)
Description:
The small GTPases Rab are key regulators of intracellular membrane trafficking, from the formation of transport vesicles to their fusion with membranes. Rabs cycle between an inactive GDP-bound form and an active GTP-bound form that is able to recruit to membranes different set of downstream effectors directly responsible for vesicle formation, movement, tethering and fusion. RAB14 is involved in membrane trafficking between the Golgi complex and endosomes during early embryonic development (By similarity). Regulates the Golgi to endosome transport of FGFR-containing vesicles during early development, a key process for developing basement membrane and epiblast and primitive endoderm lineages during early postimplantation development. May act by modulating the kinesin KIF16B-cargo association to endosomes (By similarity). Regulates, together with its guanine nucleotide exchange factor DENND6A, the specific endocytic transport of ADAM10, N-cadherin/CDH2 shedding and cell-cell adhesion. Mediates endosomal tethering and fusion through the interaction with RUFY1 and RAB4B. Interaction with RAB11FIP1 may function in the process of neurite formation.
Synonyms: FBP; RAB-14
Tractability: Small molecule: a structure with a bound ligand is known. Antibody: its Gene Ontology location is reachable by antibodies, with high confidence. PROTAC: ubiquitination databases record sites on it; its protein half-life has been measured.
Target class: Enzyme; Hydrolase
Gene: Protein-coding gene on chromosome 9 (121,178,133 to 121,223,014, reverse strand). Ensembl gene ENSG00000119396.
Subcellular location: Recycling endosome; Early endosome membrane; Golgi apparatus membrane; Golgi apparatus, trans-Golgi network membrane; Cytoplasmic vesicle, phagosome; Cytoplasmic vesicle
Subcellular location (Human Protein Atlas): Vesicles
Pathways (Reactome):
Vesicle-mediated transport: RAB GEFs exchange GTP for GDP on RABs; Translocation of SLC2A4 (GLUT4) to the plasma membrane
Immune System: Neutrophil degranulation
Metabolism: Synthesis of PIPs at the plasma membrane
Metabolism of proteins: RAB geranylgeranylation
Gene Ontology:
Molecular function: G protein activity; GDP binding; GTP binding; GTPase activity; myosin V binding; protein binding
Biological process: early endosome to Golgi transport; endocytic recycling; endosomal vesicle fusion; regulation of protein localization; fibroblast growth factor receptor signaling pathway; Golgi to endosome transport; intracellular transport; phagolysosome assembly; phagosome maturation; regulation of embryonic development; vesicle-mediated transport; defense response to bacterium
Cellular component: cilium; cytoplasmic vesicle; early endosome membrane; extracellular exosome; Golgi membrane; lysosomal membrane; phagocytic vesicle; recycling endosome; cytosol; early endosome; Golgi stack; late endosome; lysosome; nuclear outer membrane-endoplasmic reticulum membrane network; perinuclear region of cytoplasm; plasma membrane; recycling endosome membrane; rough endoplasmic reticulum; tertiary granule membrane; trans-Golgi network transport vesicle; cytoplasmic vesicle membrane; Golgi apparatus; trans-Golgi network
Genetic constraint (gnomAD): Loss-of-function variants: 1 observed, 21.15 expected, observed/expected ratio (o/e) 0.0473, 90% interval 0.016 to 0.22. The upper end of that interval is the gene's LOEUF score, 0.22, which puts it in group 1 of 6, group 1 being the genes least tolerant of losing a copy. Missense variants: 82 observed, 194.13 expected, observed/expected ratio (o/e) 0.42, 90% interval 0.35 to 0.51. Synonymous variants: 65 observed, 66.45 expected, observed/expected ratio (o/e) 0.98, 90% interval 0.8 to 1.2.
Homologues: Orthologues: chimpanzee RAB14 (100% identical), dog RAB14 (100% identical), guinea pig RAB14 (100% identical), macaque RAB14 (100% identical), mouse Rab14 (100% identical), rabbit RAB14 (100% identical), rat Rab14 (100% identical), tropical clawed frog rab14 (100% identical), zebrafish rab14 (96% identical), pig RAB14 (91% identical), Caenorhabditis elegans rab-14 (83% identical), Drosophila melanogaster Rab14 (81% identical). Paralogues in human: RAB4A (59% identical), RAB2B (57% identical), RAB4B (57% identical), RAB2A (55% identical), RAB11B (46% identical), RAB11A (45% identical), RAB39A (40% identical), RAB25 (40% identical), RAB1B (39% identical), RAB1A (39% identical), RAB37 (39% identical), RAB39B (39% identical), and 56 more.
Diseases named in the same sentence as RAB14 in open-access papers:
RAB14 is named in the same sentence as 54 diseases in open-access papers, as found by Europe PMC text mining. Sharing a sentence is not in itself a finding about the gene and the disease. The quoted sentences say what the papers report.
gastric cancer (8 papers, 2017 to 2021). A primary or metastatic malignant neoplasm involving the stomach. "The reintroduction of RAB14 partially abrogated its miR-320a-mediated downregulation and reversed the miR-320a-induced effects on gastric cancer cell proliferation." (PMID 33391397, 2021). "hsa-miR-320a-3p serves as a negative regulator in the progression of gastric cancer by targeting RAB14." (PMID 33391397, 2021). "Alterations in RAB14 expression have been documented in gastric cancer, renal cancer, nasopharyngeal carcinoma and lung cancer." (PMID 32248836, 2020). "The aim of this study was to investigate the function and mechanism of Rab14 in gastric cancer cell lines." (PMID 28107526, 2017). "In summary, here we report the dysregulation expression of Rab14 in gastric cancer and found that Rab14 functions as an oncogene in gastric cancer cells by targeting through AKT pathway." (PMID 28107526, 2017). "Although much has been learned about the role of Rab14 in the phagosomal systems and biosynthetic/recycling pathway, there were still little open-published studies regarding the expression and function of Rab14 in human cancer particular gastric cancer." (PMID 28107526, 2017). "In this study, we show that Rab14 presents a significant up-regulated expression among the paired tissue samples and cell lines in gastric cancer." (PMID 28107526, 2017). "Previous study confirmed that the mRNA expressions levels of RAB14 in gastric cancer was significantly higher than that in healthy gastric mucosa and the abnormal expression of RAB14 in gastric cancer promotes the malignant development of tumor by activating Akt signaling pathway." (PMID 34282711, 2021). "According to previous research, the mRNA expression of RAB14 in gastric cancer is dramatically higher than that in healthy gastric mucosa; the abnormal expression of RAB14 in gastric tumors promotes the malignant development of tumors by activating the Akt signaling pathway." (PMID 34282711, 2021). "Increasing reports have identified various downstream genes of miR-320a including programmed cell death protein 1 (PD1) in malignant mesothelioma, interleukin 4 in preeclampsia, microtubule-associated protein 9 (MAP9) in postmenopausal osteoporosis, and Rab protein 14 (RAB14) in gastric cancer." (PMID 34720057, 2021). "In conclusion, this study provides a new evidence on that Rab14 functions as a novel tumor oncogene and could be a potential therapeutic target in gastric cancer." (PMID 28107526, 2017). "This is a novel evidence to demonstrate the overexpression of Rab14 and may provide a new direction in prognosis or therapy of gastric cancer." (PMID 28107526, 2017). "It was reported that miRNA-338-3p could directly target PREX2a, MACC1, Rab14, RAB23, IRS2, and Sox4 in ovarian cancer, gastric cancer, breast tumor, prostate cancer, non-small cell lung cancer, glioblastoma, and neuroblastoma." (PMID 33817311, 2021). "Among the 17 paired samples, 11 of them (65%) exhibited a higher (Fold change≥2) expression of Rab14 in gastric cancer tissues compared to the matched non-tumor gastric tissues." (PMID 28107526, 2017). "Nevertheless, the role of Rab14 in the pathogenesis of gastric cancer is still not clear." (PMID 28107526, 2017).
bladder cancer (7 papers, 2012 to 2024). "Previous studies have shown that the RAB14 gene can promote the development of bladder cancer and non‐small‐cell lung cancer." (PMID 39538416, 2024). "Collectively, our results suggested that the promotion effects of RAB14 on the migration and invasion abilities of bladder cancer cells likely worked through the autophagy-EMT pathway." (PMID 37558664, 2023). "In a different study it was revealed that RAB14 has a carcinogenic effect in bladder cancer by downregulating SHC1 expression." (PMID 35601500, 2022). "In bladder cancer, RAB14 overexpression was correlated with advanced stage and poor prognosis and was shown to activate the MAPK1/MAPK8 signaling pathway to enhance cellular migration and invasion." (PMID 36471277, 2022).
lung carcinoma (6 papers, 2012 to 2025). "This miRNA interacted with RAB14 instead, which promotes the proliferation and invasion of lung cancer." (PMID 37754243, 2023). "A recent proteomics study also identified several trafficking-related proteins (e.g., Rab14) when members of miR-17-92 cluster were down-regulated in SBC-3 lung cancer cells." (PMID 23285084, 2012). "RAB14 overexpression was also associated with increased growth rate, cell invasion and cell cycle progression, while also increasing expression of cyclins involved in cell cycle progression such as cyclins D and E and CTGF in cell lung cancers." (PMID 33546420, 2021).
breast carcinoma (5 papers, 2020 to 2024). "It has also been shown that RAB14 is a miR-320a target in breast cancer; thus, silencing RAB14 inhibits proliferation, migration, and invasion of breast cancer cell lines." (PMID 39376611, 2024). "RAB14 inhibition mediated by miR-320a suppresses cell proliferation, migration, and invasion in breast cancers." (PMID 39376611, 2024). "However, RAB14 actively interacts with Nischarin by regulating the production of exosomes in breast cancer cells, subsequently affecting tumor cell adhesion, cell migration, tumor growth, and metastasis." (PMID 39376611, 2024). "It has been shown that LINC00963 functioned as a competitive endogenous RNA for miR-214-5p/RAB14 in esophageal cancer, miR-625/ HMGA1 or miR-324-3p/ ACK1 axises in breast cancer." (PMID 32357409, 2020).
colorectal cancer (5 papers, 2020 to 2022). A primary or metastatic malignant neoplasm that affects the colon or rectum. "A positive DUXAP8/miR‐577/RAB14 feedback loop promotes cell migration and invasion in colorectal cancer." (PMID 32248648, 2020).
osteosarcoma (5 papers, 2017 to 2023). A usually aggressive malignant bone-forming mesenchymal neoplasm, predominantly affecting adolescents and young adults. "In addition, lncRNA-CASC15 was shown to be overexpressed in osteosarcoma plasma exosomes and promote osteosarcoma progression through the regulation of the miR-338-3p/RAB14 axis." (PMID 37377390, 2023). "Thus, we conclude that Rab14 can promote GC cells carcinogenesis through AKT signaling pathway, which is in agreement with previous research in human osteosarcoma U20S cells." (PMID 28107526, 2017).
ovarian carcinoma (5 papers, 2021 to 2023). A malignant neoplasm originating from the surface ovarian epithelium. "RAB14, in particular, was associated with aggressiveness of ovarian cancer cells since it promoted cell proliferation through the Wnt signaling pathway." (PMID 33546420, 2021). "The increased expression of RAB14 in ovarian cancer promotes tumor cell proliferation and invasion through the Wnt signaling pathway." (PMID 34282711, 2021). "In addition, the increased expression of RAB14 in ovarian cancer promotes tumor cell proliferation and invasion through Wnt signaling pathway, which is associated with poor prognosis." (PMID 34282711, 2021). "RAB14’s relevance in cancer proliferation is also substantiated by evidence that upon overexpression, the Wnt and AKT signaling pathways are activated in gastric and ovarian cancers." (PMID 37754243, 2023).
cervical cancer (4 papers, 2020 to 2022). A primary or metastatic malignant neoplasm involving the cervix. "For example, cytoplasmic TMPO-AS1 absorbed miR-577 to upregulate RAB14, thereby promoting the proliferation and migration of cervical cancer cells." (PMID 35040749, 2022). "In addition, TMPO-AS1 is also overexpressed in cervical cancer and sponges miR-577 to increase RAB14 expression to enhance cancer progression." (PMID 34330309, 2021). "A positive TMPO‐AS1/miR‐577/RAB14 feedback loop facilitates the progression of cervical cancer." (PMID 32248648, 2020).
COVID-19 (4 papers, 2022 to 2023). A disease caused by infection with severe acute respiratory syndrome coronavirus 2. "Additionally, whole genome analysis of COVID-19 lung tissue identified RAB14 polymorphisms that alter its binding to some miRNAs." (PMID 35239653, 2022). "High levels of circulating GCNT4, RAB14, C1GALT1C1, CD207 and ABO have also been previously suggested to be causally associated with an increased risk of suffering from critical COVID-19, with comparable odds ratios varying from 1.12 to 1.35." (PMID 37958866, 2023). "One study identified RAB14 GTPases as a critical COVID-19 host factor: coronaviruses hijack Rab GTPase in host cells to replicate." (PMID 35239653, 2022). "However, our Mendelian randomization analyses showed that higher BMI is causal for higher levels of the COVID-19 protective proteins SELE, KEL, SELL, and causal for lower levels of the COVID-19 risk increasing proteins C1GALT and RAB14." (PMID 35239653, 2022). "Moreover, some genes related to protein secretion and reactive oxygen species pathways like MAPK1, RAB14, RAB22A, SOD1, and CAT were dysregulated in COVID-19 versus other-viral diseases." (PMID 35922752, 2022). "Herein, we have identified a panel of four miRNA targeting ACE2 and RAB14 genes significantly up-regulated in the serum of COVID-19 critical patients compared with asymptomatic or negative individuals." (PMID 35721225, 2022).
hepatocellular carcinoma (4 papers, 2019 to 2022). A malignant tumor that arises from hepatocytes. "Choroideremia-like protein (CHML), a member of the Rab escort protein (REP) family, promotes migration, invasion and metastasis of hepatocellular carcinomas (HCC) cells by facilitating Rab14 recycling." (PMID 34868956, 2021). "Here, the authors show that expression of choroideremia-like (CHML) is elevated and associates with poor prognosis in hepatocellular carcinoma, and mechanistically CHML promotes metastasis in a Rab14-dependent manner." (PMID 31175290, 2019). "RAB14 recycling by CHML was shown to enhance cellular migration and invasion through improved trafficking of regulators of metastasis such as Mucin 13 and CD44 to the cell membrane in hepatocellular cancer." (PMID 36471277, 2022).
non-small cell lung carcinoma (4 papers, 2017 to 2023). A group of at least three distinct histological types of lung cancer, including non-small cell squamous cell carcinoma, adenocarcinoma, and large cell carcinoma. "Overexpression of RAB14 led to the proliferation and invasion of non-small cell lung cancers by regulating Yap signaling pathway." (PMID 37558664, 2023). "Rab14 is the final member of Rab11 subfamily and was identified as oncogene negatively regulated by miR-451 or miR-338-3p at the posttranscriptional level via binding to 3‘-UTR in non-small cell lung carcinoma (NSCLC) cells." (PMID 28107526, 2017).
oral squamous cell carcinoma (4 papers, 2020 to 2021). "Further, KCNQ1OT1 facilitated invasion and inhibited apoptosis in oral squamous cell carcinoma by regulating the miR-185-5p/Rab14 axis." (PMID 34917682, 2021). "For instance, KCNQ1OT1 was found to regulate Rab14 expression, a target of miR-185-5p, in oral squamous cell carcinoma cells as a ceRNA." (PMID 33224264, 2020).
chlamydial infection (3 papers, 2016 to 2021). "Taken together, our findings indicate that targeting the Akt/AS160/Rab14 axis could constitute a novel strategy to limit chlamydial infections, mainly for those caused by antibiotic-resistant bacteria." (PMID 31001235, 2019). "Taken together, these results indicate that Rab14 exerted limited effects on persistent chlamydial infection." (PMID 34169005, 2021). "Previous studies have identified that in acute chlamydial infection, C. trachomatis requires Akt pathway phosphorylation and Rab14-positive vesicles to transmit essential lipids from the Golgi apparatus in survival and replication." (PMID 34169005, 2021). "In summary, we have provided evidence that Rab14 recruitment and Akt phosphorylation differ between persistent and acute chlamydial infections." (PMID 34169005, 2021). "To determine the effect of Rab14 in acute and persistent chlamydial infection, we knocked down the expression of Rab14 in the HeLa cells using short interfering RNA (siRNA) transfection." (PMID 34169005, 2021). "The fragmentation of the Golgi membrane ribbon during chlamydial infection is also dependent on the Rab GTPases Rab6, Rab11, and Rab14 and is thought to be required for the expansion of the replication compartment and bacterial growth." (PMID 27703074, 2016). "Therefore, Akt appears to be a more valuable upstream therapeutic target than Rab14 in persistent chlamydial infection." (PMID 34169005, 2021). "However, the roles that Akt phosphorylation and Rab14 play in persistent chlamydial infection remain unclear." (PMID 34169005, 2021). "Therefore, inhibition of Akt or downstream members of the Akt/AS160/Rab14 axis may limit chlamydial infection." (PMID 31001235, 2019). "Summarizing, we have determined that the activation of Akt induced by chlamydial infection leads to phosphorylation and inactivation of AS160 and the subsequent recruitment to inclusions of Rab14." (PMID 31001235, 2019). "Taken together, Rab14 may not be the main downstream effector of Akt phosphorylation in persistent chlamydial infections." (PMID 34169005, 2021). "Therefore, we suspected that in persistent chlamydial infection, Akt phosphorylation may influence Chlamydia development and regulate Golgi fragmentation without involving Rab14." (PMID 34169005, 2021). "Therefore, we suspect that the effects of Akt phosphorylation on Chlamydia development may not be mediated by Rab14 in persistent chlamydial infection." (PMID 34169005, 2021).
esophageal cancer (3 papers, 2020 to 2023). A primary or metastatic malignant neoplasm involving the esophagus. "Our results suggest that miR-214-3p is a key regulator of RAB14 expression and provide further evidence of the important tumor suppressive function of miR-214-3p in esophageal cancer cells." (PMID 36471277, 2022). "Conversely, expression of RAB14 mRNA and protein were markedly upregulated in the esophageal cancer lines compared to hESO cells." (PMID 36471277, 2022). "The current study was designed to assess the expression levels of miR-214-3p and RAB14 in esophageal cancer cell lines as well as in human esophageal cancer specimens." (PMID 36471277, 2022). "In this study, we examined the interaction between miR-214-3p and RAB14, a membrane trafficking protein shown to exert oncogenic functions in other malignancies, in esophageal cancer cells." (PMID 36471277, 2022). "Functional, binding, and phenotypic assays were performed to characterize the interaction between miR-214-3p and RAB14 mRNA in esophageal cancer cells." (PMID 36471277, 2022). "Our results are the first to describe a role for RAB14 in esophageal cancer and consistent with previous reports of RAB14 affecting cellular migration and invasiveness in other malignancies." (PMID 36471277, 2022).